ANGPT1 (angiopoietin 1)
Diseases named in the same sentence as ANGPT1 in open-access papers (continued):
Sharing a sentence is not in itself a finding about the gene and the disease.
hepatocellular carcinoma (8 papers, 2012 to 2021). A malignant tumor that arises from hepatocytes. "Vegfα mRNA showed a consistent higher expression in AS-30D samples in comparison with normal fresh hepatocytes, while Angpt1 mRNA was highly expressed in normal hepatocytes, and lightly expressed in hepatoma cells." (PMID 34737944, 2021). "Angiopoietin-1 (Ang-1) and angiopoietin-2 (Ang-2) play critical roles in angiogenesis in hepatocellular carcinoma (HCC)." (PMID 30701027, 2018). "Moreover, the same study showed that angiopoietin-1 and angiopoietin-2 can be detected in hepatoma cells, HSCs, and smooth muscle cells." (PMID 30959975, 2019). "Moreover, ephrinA1 affects hepatoma cell growth by regulating the expression of genes related to cell cycle (p21), angiogenesis (angiopoietin 1 and thrombospondin 1), and cell–cell interactions (Rho, integrin, and matrix metalloproteinases) in cultured hepatoma cells." (PMID 33572758, 2021). "Studies have shown that the activation of hepatic stellate cells (HSCs) can secrete angiopoietin-1 (ANG-1), thereby promoting angiogenesis in hepatocellular carcinoma." (PMID 33722297, 2021).
myocardial infarction (8 papers, 2012 to 2023). Gross necrosis of the myocardium, as a result of interruption of the blood supply to the area, as in coronary thrombosis. "Sustained local release of vascular endothelial growth factor and angiopoietin-1 after injection within PEG-Fb microspheres has been demonstrated in a rat myocardial infarction model with intramyocardial injection." (PMID 32019556, 2020). "The concentration of sTie2 is increased in a range of conditions, including peripheral arterial disease and myocardial infarction, where it has been suggested to bind and block Angpt1 resulting in vascular dysfunction." (PMID 28623351, 2017). "We have previously reported that angiopoietin-1 significantly reduced myocardial infarction after ischemic injury and protected cardiomyocytes from oxidative stress-induced apoptosis." (PMID 23554782, 2012). "We found in the Lin− group that several angiogenic trophic factors (vascular endothelial growth factor, Angiopoietin-1, basic fibroblast growth factor, platelet-derived growth factor-aa) plasma level significantly increased to the 4th day after myocardial infarction." (PMID 31284593, 2019). "In a rat model of myocardial infarction, UCB isolated HSCs overexpressing VEGF and PDGF (platelet-derived growth factor gene), or VEGF and angiopoietin-1 (Ang1) genes inhibited the development of cardiac muscle necrosis and increased capillary density in the myocardium." (PMID 37509661, 2023).
cerebral malaria (7 papers, 2009 to 2025). A sequestration of Plasmodium falciparum in the brain, which can cause coma and/or seizures. "Patients with cerebral malaria frequently exhibit markedly high Angiopoietin-2–Angiopoietin-1 ratios, reflecting profound endothelial activation." (PMID 41002937, 2025). "Here, we find that in a murine model of cerebral malaria, intravenous whole blood restored the balance of angiopoietin 1 and 2, key factors that regulate endothelial inflammation and barrier integrity." (PMID 36700582, 2023). "Dysregulation of angiopoietin-1 (ANG-1) plays a mechanistic role in the pathogenesis of cerebral malaria while plasma levels of especially ANG-2, positively correlates with disease severity." (PMID 35222377, 2022).
colon carcinoma (7 papers, 2002 to 2025). "The discrepancies of angiogenic expression in tumor cells between angiopoietin-1 and angiopoietin-2 have been reported in multiple types of cancer, including oral cancer, gastric cancer, and colon cancer." (PMID 32799882, 2020). "Human colon cancer cells (KM12L4) were transfected with vector (pcDNA) alone (control) or vector containing angiopoietin-1 and injected into the peritoneal cavities of mice." (PMID 12402160, 2002). "P125A-endostatin also displayed improved inhibition of colon cancer growth in athymic mice, and greater downregulation of human vascular endothelial growth factor (VEGF) and human angiopoietin 1 (Ang1) from tumours." (PMID 15083196, 2004). "In patients with colon carcinoma (n = 262), high ANGP2 and VEGF‐A expression, individually, predicts a somewhat worse probability of survival compared to low ANGPT2 or VEGF‐A expression, whereas high or low ANGPT1, PDGFA, and FGF2 expression has no impact." (PMID 34102002, 2021).
COVID-19 (7 papers, 2021 to 2024). A disease caused by infection with severe acute respiratory syndrome coronavirus 2. "Dexamethasone decreases the ratio of angiopoietin-2 to angiopoietin-1, thereby promoting endothelial stabilization and reducing endothelial cell apoptosis, which is critical in reducing mortality in critically ill COVID-19 patients." (PMID 39861839, 2024). "In our study, we analyzed the Angiopoietin-1 and Angiopoietin-2 indexes and Angiopoiten-2/Angiopoiten-1 ratio as indicators that will serve as a screening tool for severity in COVID-19 patients in delta and omicron waves." (PMID 38785513, 2024). "Angiopoietin-1 mRNA levels were downregulated in renal tissue from both COVID-19 (fold change 0.27, p < 0.0001) and bacterial sepsis patients (fold change 0.67, p < 0.0001) compared to controls." (PMID 34112226, 2021). "Patients with cardiovascular failure and hypotension requiring intravenous pressors showed lower IL-7 levels later in their COVID-19 trajectory, while CXCL5, IL-12, and ANGPT-1 levels were depressed early during the course of infection." (PMID 34177897, 2021). "In addition, severe COVID-19 patients have increased circulating levels of angiogenic factors, such as VEGF-A, ANGPT1, ANGPT2, and TGF-β." (PMID 36769357, 2023).
prostate carcinoma (7 papers, 2012 to 2025). A carcinoma that arises from epithelial cells of the prostate gland. "The overexpression of LEP and ANGPT1 by PP adipose tissue in OB/OW men may contribute towards a favorable environment for prostate cancer progression." (PMID 23009291, 2012). "High levels of stromal DKK-3 in benign prostatic hyperplasia (BPH) and prostate cancer (PCa) have been reported to increase fibroblast proliferation, promote myofibroblast differentiation, and contribute to the angiogenic switch by suppressing vessel-stabilizing factors like angiopoietin-1 (ANGPT1)." (PMID 38201279, 2023). "The genes ITGBL1, DSC3, COL4A6, ANGPT1, ARMCX1, MICAL2, and EPHA5 have been recognized as pivotal genes that substantially affect the microenvironment of prostate cancer." (PMID 40943497, 2025). "For example, platelets isolated from breast cancer patients contain a higher level of VEGF and angiopoietin 1 (Ang-1), while platelets from prostate cancer patients show a greater level of VEGF but not Ang-1." (PMID 28737696, 2017).
cervical cancer (6 papers, 2013 to 2024). A primary or metastatic malignant neoplasm involving the cervix. "The important role of angiopoietin 1 is evidenced by papers on its effect on endometrial bleeding and its beneficial effect in reducing the risk of early cervical cancer metastasizing to lymph nodes." (PMID 39000274, 2024). "The present study was aimed at investigating the diagnostic and prognostic values of serum angiopoietin 1 and 2 (sAng-1 and sAng-2) in cervical cancer." (PMID 28584715, 2017). "The increased ANGPT1 expression in HeLa cells by transgene promotes the growth of human cervical cancers in mice via promoting tumor angiogenesis." (PMID 24379889, 2013). "Interestingly, we observed a reciprocal change in angiopoietin-1 and angiopoietin-2 transcripts in endothelial cells treated with cervical cancer exosomes and shifting of the angiopoietin balance towards angiopoietin-2." (PMID 34167524, 2021).
ischemia (6 papers, 2013 to 2022). A hypoperfusion of the BLOOD through an organ or tissue caused by a PATHOLOGIC CONSTRICTION or obstruction of its BLOOD VESSELS, or an absence of BLOOD CIRCULATION. "EphA4 also negatively regulates EC expression of angiopoietin-1, MCP-1 and MMP2 which may have a profound effect on collateral density during development and/or remodeling following ischemia." (PMID 27467069, 2016).
lung injury (6 papers, 2010 to 2022). "It has been shown that BM-MSCs genetically modified to secrete more angiopoietin-1 (ANG-1) had both a protective and an alleviating therapeutic effect on pulmonary vascular endothelial permeability caused by induced acute lung injury." (PMID 35741711, 2022). "The decline in ANGPT-1 and increase in ANGPT-2 correspond with marked blood-brain barrier breakdown after brain injury." (PMID 30086801, 2018). "In a severe acute lung injury (ALI) mouse model, treatment with bone marrow-derived MSCs modified to express human angiopoietin 1 (Ang1) promoted a significant reduction in airspace inflammation, with 96 % less neutrophils than groups treated with control MSCs or saline." (PMID 32974331, 2020).
rheumatoid arthritis (6 papers, 2015 to 2021). A chronic, systemic autoimmune disorder characterized by inflammation in the synovial membranes and articular surfaces. "As with the original DMG-alone analysis, the MEGs were also significantly 3.75-fold enriched in the KEGG ‘Rheumatoid arthritis‘ pathway (q = 1.70E-02, where q is a multiple-test corrected P-value) with 7 out of 89 genes: ANGPT1, CSF2, CTLA4, HLA-DQA1, HLA-DQA2, HLA-DRA and HLA-DRB1." (PMID 25901943, 2015). "For instance, a study detected US synovitis of wrist joints in 50 early rheumatoid arthritis patients, and disclosed PD-US synovitis showed positive correlation with TNF-α, IL-6, and angiopoietin-1 and -2 levels." (PMID 31778437, 2019).
Alzheimer disease (5 papers, 2012 to 2024). A progressive, neurodegenerative disease characterized by loss of function and death of nerve cells in several areas of the brain leading to loss of cognitive function such as memory and language. "In their study, the authors investigated serum levels of the proangiogenic factor Angiopoietin-1 in patients with Alzheimer's disease, mild cognitive impairment, and controls." (PMID 23365784, 2013). "They found higher levels in patients with Alzheimer's disease and concluded that Angiopoietin-1 is a potential candidate for a respective biomarker panel." (PMID 23365784, 2013).
Cerebral ischemia (5 papers, 2019 to 2023). Restriction of arterial blood supply to the brain associated with insufficient oxygenation to support the metabolic requirements of the tissue. "Previous works performed in a rat model of cerebral ischemia and in HUVEC cells showed an involvement of HMGA1 in modulating angiogenic proteins, such as Angiopoietin-1, a factor fundamental in maintaining the tumor vascularization." (PMID 31311575, 2019).
pancreatic cancer (5 papers, 2013 to 2021). "In this study, we first reported that ANGPT1 may be an important underlying regulator that is involved in MCT-induced angiogenesis in pancreatic cancer." (PMID 27240355, 2016). "With particular reference to pancreatic cancer, preclinical in vivo data suggest that mast cell tryptase plays a role in stimulating angiogenesis and cancer growth also via the activation of the proangiogenic factor angiopoietin-1." (PMID 33669751, 2021). "Interestingly, the serum MCT level was less correlated with two important pro-angiogenic factors, VEGF or PDGF, in pancreatic cancer patients, but highly related to ANGPT1 and TIE2 expression levels." (PMID 27240355, 2016). "Our findings suggest that MCT plays an important role in pancreatic cancer angiogenesis and tumor growth via activating the angiopoietin-1 pathway, and tryptase inhibitors may be evaluated as an effective anti-angiogenetic approach in pancreatic cancer therapy." (PMID 27240355, 2016). "PHD2 overexpression in the pancreatic cancer cells MIA PaCa-2 and PANC-1 decreased tumor growth by suppressing tumor vasculature in an HIF-dependent way resulting from decreases seen in VEGF and angiopoietin-1 (ANGPT1)." (PMID 29896451, 2018). "Similar to clinical specimens, the MCT-treated nude mice bearing pancreatic tumor had higher expression levels of ANGPT1, while nafamostat co-injection partly suppressed the effect of MCT, which added the speculation that MCT regulated ANGPT1 expression to affect angiogenesis in pancreatic cancer." (PMID 27240355, 2016).
acute lung injury (4 papers, 2011 to 2024). A condition of lung damage that is characterized by bilateral pulmonary infiltrates (pulmonary edema) rich in neutrophils, and in the absence of clinical heart failure. "The transfection of mesenchymal stem cells (MSCs) using a minicircle expressing the human angiopoietin 1 (ANGPT1) enhanced the MSC therapy by mediating a reduced pulmonary inflammation and lung permeability in lipopolysaccharide-induced acute lung injury (ALI) in mice." (PMID 38540320, 2024). "MSC-secreted angiopoietin-1 (Ang-1) and keratinocyte growth factor (KGF) enhance restoration of disrupted alveolar–capillary barrier, while specific regulatory mRNAs in EVs mediate the protective effects of MSCs in pre-clinical models of bacterial or non-infectious acute lung injuries." (PMID 34970706, 2021).
Astrocytomas (4 papers, 2011 to 2025). "Astrocytomas express growth factors and receptors that are typically induced during angiogenesis; one of them is angiopoietin-1 (ANGPT1)." (PMID 31861636, 2019). "Here, applying decision tree classification algorithm we performed astrocytoma specific protein profile analysis on serum proteins TIMP-1, active and latent form of TGF-β1, IP-10, ANGPT-1, OPN, and YKL-40 using enzyme-linked immunosorbent detection assay (ELISA)." (PMID 34162919, 2021). "Here we showed that protein levels of TIMP-1, OPN, YKL-40, and active form of TGF-β1 in astrocytoma patient serum substantially differed as compared to control (healthy) group, while the differences between healthy control and meningioma group were observed only for ANGPT-1 and TGF-β1 active." (PMID 34162919, 2021). "A profile with a relatively small number of proteins (ANGPT1, TIMP1, IP10, TGFβ1) was sufficient to correctly assign 79.7% (47/59) of the astrocytoma and 65.1% (28/43) of the control subjects." (PMID 31861636, 2019). "TIMP-1, ANGPT-1 and active form of TGF-β1 demonstrated the tendency of patient survival association with the lower protein level in astrocytoma, but the difference was not significant." (PMID 34162919, 2021). "The decision tree classification analysis was performed using “Classification Learner” application provided by MathWorks MatLab on TIMP-1, ANGPT-1, OPN, IP-10, TGF-β1 active, TGF-β1 latent and YKL-40 protein expression levels in astrocytoma patients and healthy control groups." (PMID 34162919, 2021). "To elucidate if the protein level in blood serum is related with the presence of brain tumours, we investigated the mRNA expression of TIMP-1, ANGPT1, SPP1 (OPN coding gene), IP-10, TGF-β1 and TIMP-1 in astrocytoma samples as well as in healthy human brain tissue." (PMID 34162919, 2021). "In conclusion, the serum protein profiles of ANGPT1, TIMP1, IP10, and TGFβ1 were associated with the presence of astrocytoma independent of its malignancy grade, while OPN and IP10 were associated with GBM patient survival." (PMID 31861636, 2019).
breast tumor (4 papers, 2016 to 2024). "Alternatively, NPI was positively correlated with ANGPT1 mRNA levels expressed in breast tumor tissues (r = 0.079, p<0.001)." (PMID 39302921, 2024). "Congruently, we found an inverse correlation between the expression of mR-204 and ANGPT1 and TGFβR2 in breast tumors and cancer cell lines." (PMID 27703260, 2016). "Accordingly, an inverse correlation between miR-204 and ANGPT1/TGFβR2 expression was found in breast tumors." (PMID 27703260, 2016). "In order to extend our observations, then we evaluated if miR-204 suppression in clinical breast tumors correlates with the increased expression of ANGPT1 and TGFβR2 proteins." (PMID 27703260, 2016). "A possible mechanism is that the ZNF350/BRCA1/CtTB-interacting protein complex represses the expression of angiopoietin-1 (ANG1) and high-mobility group AT-hook 2 (HMGA2), which are commonly involved in the proliferation and vascularization during breast tumor formation." (PMID 30613364, 2018).
congenital glaucoma (4 papers, 2020 to 2024). "We did not identify pathogenic or likely pathogenic variants in other genes known to cause congenital glaucoma, including rare variants (allele frequency <0.001) in ANGPT1, CPAMD8, CYP1B1, MYOC, LTBP2, PITX2, SVEP1, and TEK." (PMID 36453543, 2022). "As THBS1 can contribute to the development of vasculature as well as lymphangiogenesis, we first considered abnormalities in angiogenesis, lymphangiogenesis, or SC development, as has been recently shown for congenital glaucoma causing mutations in ANGPT1 and TEK." (PMID 36453543, 2022). "Supporting these mouse studies, human genetic studies show that both Tie2 and Angpt1 loss-of-function variants associate with risk of congenital glaucoma, and single-nucleotide polymorphisms in the Angpt1 promoter region significantly associate with ocular hypertension and OAG risk." (PMID 33315051, 2020). "–20 Disruption of the Tie2 pathway in mice, by conditional knockout of Tie2 or its ligands (Angpt1 and Angpt2) early in postnatal development, results in failure of SC formation, which is associated with increased IOP and optic nerve pathology resembling human congenital glaucoma." (PMID 33315051, 2020).
diabetic retinopathy (4 papers, 2020 to 2023). "The objective of this study was to investigate the association between SNPs in the TIE2 and ANGPT-1 genes and diabetic retinopathy (DR)." (PMID 37249455, 2023). "Notably, diabetic retinopathy is phenocopied by retinal ANGPT2 overexpression, whilst ANGPT1 overexpression can retard the development of diabetic retinopathy and nephropathy." (PMID 34460911, 2021).
endotoxemia (4 papers, 2011 to 2025). "For example, we found that S1 and endothelial cells communicate with the Angpt1 (Angiopoetin 1) and Tek (Tie2) ligand-receptor pair at baseline and throughout the endotoxemia timeline." (PMID 33448928, 2021). "Angpt1 also reinforces the endothelial tight junctions during endotoxemia and prevents VEGF-induced endothelial permeability." (PMID 30760202, 2019).
fibrosis (4 papers, 2013 to 2026). the formation of excess fibrous connective tissue in an organ or tissue in a reparative or reactive process. "In the current study we show for the first time that loss of Angpt1 increases tubulointerstitial fibrosis and capillary rarefaction in a murine model of fibrosis, UUO." (PMID 29293543, 2018). "Increasing Angpt1 demonstrated beneficial effects in several models of fibrosis including UUO, cyclosporine induced injury, and ischemia-reperfusion injury, with attenuated tubular injury and tubulointerstitial fibrosis while protecting peritubular capillaries." (PMID 29293543, 2018).
gastric cancer (4 papers, 2010 to 2022). A primary or metastatic malignant neoplasm involving the stomach. "15d-PGJ2 exerts anti-angiogenic activity by inhibiting VEGF and angiopoietin-1 (Ang-1) in renal cancer and gastric cancer, respectively." (PMID 34335286, 2021). "Inhibition of angiopoietin-1 by antisense expression vector was shown to reduce tumorigenesis and angiogenesis of gastric cancer xenografts in nude mice." (PMID 20369064, 2010). "Angiopoietin-1 and -2 are reported to be highly expressed in human gastric cancer." (PMID 20369064, 2010).